CD82 (CD82 molecule)
Diseases named in the same sentence as CD82 in open-access papers (continued):
Sharing a sentence is not in itself a finding about the gene and the disease.
lymph node metastasis (13 papers, 2011 to 2025). "In terms of cell motility regulation, CD9, CD63 and CD82 are metastasis suppressors and the expression level is inversely associated with lymph node metastasis." (PMID 34222025, 2021). "In the multivariate logistic regression analysis, depth of invasion, KAI1/CD82 and β-catenin were significantly associated with lymph node metastasis, while KAI1/CD82 was significant associations with distant metastasis." (PMID 26408312, 2015). "In our research, we found that CD82 protein expression was negatively linked to the advanced stage, grade, and lymph node metastasis." (PMID 25889325, 2015). "PTC cases with low expression of KAI-1/CD82 RNA by tumor cells were more often associated with extrathyroid extension of the disease and with lymph node metastasis." (PMID 28548071, 2014). "Furthermore, in our analysis, KAI1/CD82 expression was shown as a significant risk factor for lymph node metastasis." (PMID 26408312, 2015). "Of notice, CD82 staining was restricted to plasma membrane in patients with lymph node metastasis, but was distributed diffusely in the cytoplasm as well as on the plasma membrane in primary tumor." (PMID 28030805, 2017). "In NPC, the underexpression of the KAI1/CD82 protein was found to correlate with lymph node metastasis." (PMID 25789023, 2015). "Multivariate logistic regression analysis showed that KAI1/CD82 and β-catenin expression were significantly associated with lymph node metastasis and KAI1/CD82 was significantly associated with distant metastasis." (PMID 26408312, 2015). "However, the expression of KAI1/CD82 protein expression was found to correlate with lymph node metastasis." (PMID 25789023, 2015). "It is concluded that the expression of CD133 and KAI1/CD82 protein could be correlated with lymph node metastasis, grade of tumor, and pTNM stage in LSCC, and also concluded that they are useful prognostic factors for OS and DFS in LSCC." (PMID 24758564, 2014). "In the 83 LSCC patients, a univariate analysis revealed that the DFS survival significantly correlated with expression of CD133 (P < 0.001) and KAI1/CD82 (P < 0.001), tumor location (P = 0.033), grade of tumor (P = 0.002), lymph node metastasis (P = 0.004), and pTNM stages (P < 0.001)." (PMID 24758564, 2014). "In addition, the KAI1/CD82 gene was expressed at low levels in nasopharyngeal carcinoma tissues, while high expression was identified in non-neoplastic nasopharyngeal tissues, and was associated with lymph node metastasis." (PMID 25789023, 2015). "The positive rate of KAI1/CD82 expression was negatively correlated with pTNM stage (P = 0.014), pathological grade (P < 0.001), and lymph node metastasis (P = 0.007)." (PMID 24758564, 2014). "A multivariate analysis revealed expression of CD133 and KAI1/CD82, lymph node metastasis, and pTNM stages were independent prognostic factors for DFS and OS (P < 0.05)." (PMID 24758564, 2014). "And there was a negative relationship between the expression of CD82 protein expression and the grade of tumors, lymph node metastasis, and pTNM stage (P < 0.05)." (PMID 25889325, 2015). "However, decreased KAI1/CD82 expression correlated significantly with distant metastasis, lymph node metastasis and TNM stage." (PMID 26408312, 2015). "VM and the expressions of CD82/KAI1 and HIF-1α in NSCLC are related to differentiation, lymph node metastasis, clinical staging, and prognosis.The combined detection of CD82/KAI1, HIF-1α, and VM has an important role in predicting the progression and prognosis of NSCLC." (PMID 22152691, 2011). "The expression of KAI1/CD82 showed a negative correlation with differentiation, depth of invasion, TNM stage, distant metastasis and lymph node metastasis (P < 0.05)." (PMID 26408312, 2015). "There was a negative relationship between the expression of KAI1/CD82 protein and alcohol, histological grade, pTNM stage, and lymph node metastasis (P < 0.05)." (PMID 24758564, 2014).
colon carcinoma (11 papers, 2003 to 2026). "Publicly available transcriptomic datasets were integrated with multiplex immunohistochemistry on colon cancer tissue microarrays to characterize the cell-type-specific distribution of CD82 and its associations with key markers of T cell dysfunction." (PMID 41607790, 2026). "This study investigates the expression characteristics and functional significance of the transmembrane protein CD82 in the colon cancer immune microenvironment, with emphasis on its regulatory role in CD8+ T cell exhaustion and clinical outcomes." (PMID 41607790, 2026). "To substantiate these observations, we analyzed the relationship between actin cytoskeleton and KAI1/CD82 in the cells expressing endogenous KAI1/CD82 proteins such as HT29 colon cancer cells and PrECs." (PMID 23251627, 2012). "Although KAI1/CD82 has been reported to upregulate cell-cell adhesion or aggregation, associate with E-cadherin in colon cancer cells, and bind to a counter-receptor DARC, how KAI1/CD82 regulates cell-cell adhesion is poorly understood." (PMID 23251627, 2012). "As part of our evaluation of members of TM4SF as possible prognostic predictors, we further extended our study to the expression of CD151 and performed a retrospective study on the expression of CD151, MRP-1/CD9 and KAI1/CD82 in colon cancer." (PMID 12838318, 2003). "However, expression of another CAM molecule CD82 (KAI1) decreased in colon cancer cells although it was highly expressed in CCD18Co cell line." (PMID 30289336, 2019). "Collectively, these findings demonstrate that CD82 promotes CD8+ T cell exhaustion, contributing to tumor progression and immunotherapy resistance in colon cancer." (PMID 41607790, 2026). "KAI1/CD82 expression suppressed experimental metastasis of rat prostate tumour cells, and decreased motility and invasion of colon carcinoma cells." (PMID 12838318, 2003). "The aim of this study is to clarify the clinical significance of the member of TM4SF (MRP-1/CD9, KAI1/CD82 and CD151) in human colon cancer." (PMID 12838318, 2003). "As part of our evaluation of members of the TM4SF as possible prognostic predictors, we performed a retrospective study on the expression of the MRP-1/CD9 gene, the recently identified KAI1/CD82 gene and the CD151 gene in human colon cancer." (PMID 12838318, 2003). "We have shown that the reduction of MRP-1/CD9 and KAI1/CD82 expression, and the increasing CD151 expression are indicators for a poor prognosis in patients with colon cancer." (PMID 12838318, 2003). "We studied 146 colon cancer patients who underwent curative surgery and studied the expression of MRP-1/CD9, KAI1/CD82 and CD151 using reverse transcriptase – polymerase chain reaction and immunohistochemistry." (PMID 12838318, 2003). "The classification of colon cancers according to MRP-1/CD9, KAI1/CD82 and CD151 expression might be useful in identifying patients for whom intensive adjuvant therapy is warranted." (PMID 12838318, 2003). "Furthermore, we have shown that the survival rate for colon cancer patients with negative KAI1/CD82 expression was strikingly lower than that of patients with KAI1/CD82-positive tumours." (PMID 12838318, 2003).
non-small cell lung carcinoma (10 papers, 2011 to 2025). A group of at least three distinct histological types of lung cancer, including non-small cell squamous cell carcinoma, adenocarcinoma, and large cell carcinoma. "CD82 is also known to inhibit cancer invasion and metastasis in non-small-cell lung carcinoma (NSCLC) via multiple mechanisms." (PMID 34503296, 2021). "The correlation between VM, or Notch4, or DLL4, or KAI1/CD82 and clinicopathological characteristics in non-small cell lung cancer." (PMID 30593175, 2018). "In a retrospective study titled “Evaluation of the correlation of vasculogenic mimicry, Notch4, DLL4, and KAI1/CD82 in the prediction of metastasis and prognosis of the course of non-small cell lung cancer” a cohort of 189 patients was analyzed to assess the impact of VM on OS." (PMID 40786517, 2025). "In the article “Evaluation of the correlation of vasculogenic mimicry, Notch4, DLL4, and KAI1/CD82 in the prediction of metastasis and prognosis in non-small cell lung cancer”, the structure presented as VM could be considered a blood lake." (PMID 40786517, 2025). "The article “Expression of CD82/KAI1 and HIF-1α in non-small cell lung cancer and their relationship to vascular mimicry” was the one article from our sample, published in Chinese." (PMID 40786517, 2025).
metastatic tumors (9 papers, 2005 to 2023). "In contrast, previous studies have shown that CD82 is a tumor suppressor, and low CD82 expression has been associated with increased probability of metastatic disease." (PMID 37335526, 2023). "The suppressive function of CD82 in metastasis has been validated in various kinds of tumors, which means that the downregulation of CD82 can be a characteristic of metastatic tumors." (PMID 34540692, 2021). "The levels of CD82 are significantly reduced in cancerous tissues of HCC patients, especially in metastatic tumors and satellite metastases." (PMID 34540692, 2021).
colorectal cancer (8 papers, 2015 to 2024). A primary or metastatic malignant neoplasm that affects the colon or rectum. "CD82 protein was present in about one-third of colorectal cancer tissues compared with more than half of normal mucosal tissues." (PMID 31483122, 2019). "Furthermore, ST6Gal 1(beta-galactoside alpha-2,6-sialyltransferase)-depleted colorectal cancer cells remove tumour-metastasis suppressor kangai 1 (KAI1, also known as CD82) via exosomes as a mechanism to enhance metastatic formation." (PMID 38200509, 2024). "90K, a tumor-associated glycoprotein, which could interact with KAI1/CD82, showed antitumor activity in colorectal cancer cells via suppressing Wnt signaling with a novel mechanism of β-catenin ubiquitination." (PMID 34306081, 2021). "Additionally, a previous study also proposed that the KAI1/CD82 expression did not alter in vitro colorectal carcinoma cell proliferation, but the apparent increased ability of cell-cell adhesion and cell aggregation was observed in KAI1/CD82 transfected cells." (PMID 34306081, 2021).
bladder cancer (7 papers, 2008 to 2024). "Some gangliosides, such as GM3 and GM2, inhibited cell motility facilitated by the tetraspanins CD9 and CD82 in some tumor cell lines (for example, colorectal, haptotactic, and bladder cancer cells)." (PMID 18171481, 2008). "Low CD82 expression has been reported to correlate with increased invasiveness and decreased calcium-related cell-cell adhesion and adhesion to fibronectin in bladder cancer cell lines." (PMID 33298014, 2020). "Moreover, HGF was reported to override the motility-inhibitory effect of KAI1/CD82 in YTS1 bladder cancer cells and Du145 cells." (PMID 23251627, 2012).
leukemia (7 papers, 2015 to 2023). A malignant (clonal) hematologic disorder, involving hematopoietic stem cells and characterized by the presence of primitive or atypical myeloid or lymphoid cells in the bone marrow and the blood. "BCL2L12 expression and stimulated proliferation and engrafting of leukaemia cells suggested CD82 and BCL2L12 as promising therapeutic targets in AML." (PMID 35057823, 2022). "Another study also shows that an aggressive leukemia phenotype in AML children is related to a mechanism where KAI1/CD82 membrane organization regulates sustained PKCα signaling." (PMID 34306081, 2021). "Both articles evaluated the expression of CD82 in the self-renewing leukemia stem cell (LSC) compartments (CD34+/CD38− cells) and the CD34+/CD38+ compartments of AML cells." (PMID 28646224, 2017). "Together, these data propose a mechanism where CD82 membrane organization regulates sustained PKCα signaling that results in an aggressive leukemia phenotype." (PMID 27417454, 2016). "Although it has been demonstrated that many tetraspanins can interact with PKCα, we have chosen to focus on CD82 due to previous work demonstrating that CD82 is upregulated in several human leukemias, including AML27." (PMID 27417454, 2016). "The present study found that the use of an anti-CD82 monoclonal antibody (CD82 mAb) mobilized CD34+ leukemia cells from BM into the peripheral blood in a humanized AML murine model." (PMID 26139471, 2015). "Exposure of AML cells to CD82 mAb inhibited the survival of AML cells in vitro (data not shown), excluding the possibility that the treatment with CD82 mAb stimulated the proliferation of CD34+ leukemia cells in vivo." (PMID 26139471, 2015). "This study showed that treatment with CD82 mAb increased the population of human CD34+ leukemia cells circulating in the PB in vivo." (PMID 26139471, 2015). "A chromatin immunoprecipitation assay was performed to examine the effect of CD82 expression on the amount of EZH2 bound to the promoter regions of tumor suppressor genes in leukemia cells." (PMID 25955299, 2015). "Taken together, our results suggest that CD82 regulates the expression of EZH2 in leukemia cells via p38 MAPK signaling, resulting in both H3K27me3 and methylation in the PTEN promoter region, thereby resulting in repression of PTEN transcription." (PMID 25955299, 2015). "To determine whether CD82 expression in leukemia cells affects the amount of PTEN promoter-bound EZH2 or the trimethylation status of H3K27 in this region, we performed ChIP assays using anti-EZH2 or-H3K27me3 antibodies in EOL-1R and MOLM13 cells." (PMID 25955299, 2015). "Moreover, the p38 inhibitor, SB203580, induced EZH2 expression in CD82-downregulated leukemia cells, suggesting that p38 directly downregulated the expression of EZH2." (PMID 25955299, 2015). "We also utilized methylation-specific PCR to examine whether CD82 expression influences the methylation status of the tumor suppressor gene promoter regions in leukemia cells." (PMID 25955299, 2015). "We then examined whether CD82 inactivates p38 in leukemia cells, and found that forced expression of CD82 in EOL-1 cells results in a 5-fold decrease in the level of p-p38 and increases in both phosphorylation at the threonine residues and total EZH2." (PMID 25955299, 2015). "Thus, treatment of AML cells with CD82 mAb might enhance mobilization of CD34+ leukemia cells into the PB, although this was a transient effect." (PMID 26139471, 2015). "We next examined whether CD82-induced EZH2 repressed the levels of MMP9 in leukemia cells." (PMID 25955299, 2015). "Indeed, our results confirm that antibody-mediated inhibition of CD82 in leukemia cells interferes with DNA hypermethylation of the PTEN promoter region, and is associated with a decrease in both the level of H3K27me3 and the amount of EZH2 bound to the promoter." (PMID 25955299, 2015).
leukemia (continued). "KAI1/CD82 can also positively regulate the expression and phosphorylation of EZH2 via inactivation of p38 MAPK signaling in leukemia cells, thus suppressing differentiation programs in leukemic stem cells and augmenting their leukemogenic activity." (PMID 34306081, 2021). "Collectively from these data, we suggest the current model where the CD82 scaffold recruits and stabilizes PKCα in membrane clusters, which can sustain ERK1/2 signaling for the development of an aggressive leukemia phenotype." (PMID 27417454, 2016). "Real-time RT-PCR and western blot analysis were performed to examine the effect of CD82 knockdown on the expression of the polycomb group member, enhancer of zeste homolog 2 (EZH2), in leukemia cells." (PMID 25955299, 2015). "The present study found that CD82 positively regulates both the expression and phosphorylation of EZH2 in leukemia cells via inactivation of p38 MAPK signaling." (PMID 25955299, 2015). "In our study, CD82 inactivated p38 MAPK and downregulated expression of p16 in leukemia cells, suggesting that CD82 might inhibit senescence in CD34+/CD38− AML cells via inactivation of p38 MAPK signaling and suppression of p16 expression." (PMID 25955299, 2015). "A recent study revealed a positive correlation between CD82 and BCL2L12 expression (an antiapoptotic protein) at mRNA and protein levels due to STAT5A and AKT signaling in AML cells isolated from patients, which eventually stimulated proliferation and engrafting of leukemia cells." (PMID 34306081, 2021). "Thus, blockade of CD82 might augment the levels of MMP9 and CXCR4, resulting in mobilization of leukemia cells into the peripheral circulation." (PMID 26139471, 2015). "They showed that LSC expressed a higher amount of CD82 than CD34+/CD38+ AML cells; these findings suggested that overexpression of CD82 may render LSC able to adhere to the bone marrow (BM) niche where it appears to regulate maintenance of leukemia stem cells within the BM niche." (PMID 28646224, 2017).
hepatocellular carcinoma (6 papers, 2015 to 2025). A malignant tumor that arises from hepatocytes. "Multiple studies have shown that CD82/KAI1 serves as a key metastasis suppressor in various solid malignancies, such as renal, prostate, breast, and hepatocellular cancers." (PMID 41404065, 2025). "Approximately 20 years ago, the role of CD82 in hepatoma metastasis and prognosis has been reported." (PMID 34540692, 2021). "Furthermore, KAI1/CD82 was also demonstrated to suppress HGF-induced migration of hepatoma cells via upregulation of Sprouty2." (PMID 34306081, 2021). "A latest study also proposed that HBV may inhibit the expression of KAI1/CD82 through hypermethylation of the promoter in hepatoma cells, leading to the development of HCC." (PMID 34306081, 2021). "In hepatocellular carcinoma, reported that anti-miR-197 inhibited HCC cell motility and invasion by directly targeting CD82." (PMID 38389703, 2024).
metastatic cancers (6 papers, 2014 to 2024). A carcinoma which has spread from the original site of growth to another anatomic site. "Understanding the expression regulation and functions of CD82 in metastatic cancer is essential to target CD82 as a prognostic biomarker or therapeutic." (PMID 38473906, 2024). "Recent study has shown that KAI1/CD82 gene expression is under-regulated in most metastatic cancers." (PMID 24758564, 2014). "Many metastatic cancers with poor prognoses correlate to downregulated CD82, but exceptions exist." (PMID 38473906, 2024). "Studies have shown that the expression of KAI1/CD82 is down-regulated in most metastatic cancers." (PMID 26431493, 2015).
prostate tumor (6 papers, 2003 to 2021). "Since then, CD82 expression levels have been reported to be negatively correlated to the metastatic potential in prostate tumors and other epithelial tumors including gastric, colon, cervix, breast, skin, bladder lung, pancreas, liver, and thyroid." (PMID 33298014, 2020). "For example, genistein, an agent for re-induction of KAI1/CD82, was shown to inhibit the invasive behavior of prostate tumor cells in nude mice." (PMID 26431493, 2015). "Identification of genes and pathways regulated by CD82 in this study may provide additional insights into the role that CD82 plays in prostate tumor progression and metastasis, as well as identify potential targets for therapeutic intervention." (PMID 33298014, 2020).
acute myeloid leukemia (5 papers, 2016 to 2023). Acute myeloid leukemia (AML) is a group of neoplasms arising from precursor cells committed to the myeloid cell-line differentiation. "CD82 was up-regulated in CD34+/CD38+ acute myelocytic leukemia stem cells and increased the phosphorylation of transcription factor STAT5 to transactivate IL-10 transcription." (PMID 36941633, 2023). "A recent report from our laboratory examined the role of CD82 glycosylation with respect to acute myeloid leukemia homing." (PMID 28428953, 2017). "CD82 could significantly reduce cell death in response to daunorubicin in acute myeloid leukemia cells." (PMID 36941633, 2023). "A more recent report from our laboratory demonstrated that CD82 regulates PKCα signaling in acute myeloid leukemia (AML)." (PMID 28428953, 2017).